Y_RNA (Y RNA )
Gene: Miscellaneous RNA gene on chromosome 21 (7,663,911 to 7,664,011, reverse strand). Ensembl gene ENSG00000276546.
Homologues: Orthologues: chimpanzee Y_RNA (100% identical). Paralogues in human: Y_RNA (100% identical), Y_RNA (86% identical), RNY3 (85% identical), Y_RNA (85% identical), RNY3P1 (84% identical), Y_RNA (84% identical), RNY3P11 (83% identical), Y_RNA (83% identical), Y_RNA (82% identical), Y_RNA (81% identical), RNY3P3 (80% identical), Y_RNA (80% identical), and 95 more.